NEMP2 (nuclear envelope integral membrane protein 2)
Synonyms: TMEM194B
Tractability: Antibody: UniProt predicts a signal peptide or a membrane-spanning region. PROTAC: ubiquitination databases record sites on it.
Gene: Protein-coding gene on chromosome 2 (190,504,338 to 190,534,722, reverse strand). Ensembl gene ENSG00000189362.
Subcellular location: Nucleus inner membrane
Subcellular location (Human Protein Atlas): Nucleoplasm
Gene Ontology:
Cellular component: nuclear envelope; nuclear inner membrane
Genetic constraint (gnomAD): Loss-of-function variants: 39 observed, 37.73 expected, observed/expected ratio (o/e) 1.03, 90% interval 0.8 to 1.35. The upper end of that interval is the gene's LOEUF score, 1.35, which puts it in group 5 of 6, group 1 being the genes least tolerant of losing a copy. Missense variants: 376 observed, 425.92 expected, observed/expected ratio (o/e) 0.88, 90% interval 0.81 to 0.96. Synonymous variants: 174 observed, 160.51 expected, observed/expected ratio (o/e) 1.08, 90% interval 0.96 to 1.23.
Homologues: Orthologues: macaque NEMP2 (96% identical), chimpanzee NEMP2 (92% identical), pig NEMP2 (79% identical), rabbit NEMP2 (75% identical), dog NEMP2 (75% identical), mouse Nemp2 (71% identical), rat Nemp2 (70% identical), guinea pig NEMP2 (59% identical), zebrafish nemp2 (31% identical), Caenorhabditis elegans nemp-1 (23% identical), Drosophila melanogaster Nemp (22% identical). Paralogues in human: NEMP1 (33% identical).